BBS1 (Bardet-Biedl syndrome 1)
Diseases named in the same sentence as BBS1 in open-access papers (continued):
Sharing a sentence is not in itself a finding about the gene and the disease.
retinal degeneration (11 papers, 2015 to 2025). Degeneration of the retina. "Overall, the late transcriptional changes identified suggest that the loss of Bbs1 only indirectly affects the transcriptome as a consequence of retinal degeneration." (PMID 35277505, 2022). "Our findings identify a role for Bbs1/BBSome in OS lipid homeostasis, suggesting a pathomechanism underlying retinal degeneration in BBS." (PMID 35277505, 2022). "A retrospective study of 67 individuals with BBS caused by variants in BBS1 or BBS10, recruited from six countries, revealed that the onset and progression of retinal degeneration occur earlier and faster in BBS10-related BBS than in BBS1-related BBS." (PMID 40087798, 2025). "The marked structural and functional retinal degeneration observed in homozygous BBS1 patients underscores the importance of genotype-informed surveillance and tailored management strategies." (PMID 41552087, 2025). "This therapy uses an AAV9 vector to deliver a codon-optimized BBS1 gene directly to the subretinal space, aiming to preserve photoreceptor cells and slow retinal degeneration." (PMID 40731764, 2025). "Comparison to Bbs1M390R/M390R, a mouse model of BBS1, demonstrated that the retinal degeneration in the BBS10 mouse model is more severe." (PMID 36125046, 2022). "Patients with mutations in BBS1 generally present later than patients with mutations in BBS10, owing to a milder phenotype and a later onset of retinal degeneration." (PMID 35484558, 2022). "This international collaborative effort allowed collection of data from patients with retinal degeneration and biallelic variants in the two most commonly involved BBS genes; BBS1 and BBS10 (hereon referred to as patients with BBS1 and patients with BBS10)." (PMID 34940782, 2021). "Retinal degeneration appears earlier and is more severe in BBS10 cases as compared to those with BBS1 variants." (PMID 34940782, 2021). "Wild-type mice (with no BBS1 deficiency) treated with the wild-type BBS1 gene developed retinal degeneration." (PMID 40731764, 2025). "Building upon these preclinical successes, the first human clinical trial targeting retinal degeneration in BBS is currently in development; AXV-101 is an investigational gene therapy designed specifically for patients with the missense BBS1 M390R mutation, the most common genetic cause of BBS." (PMID 40731764, 2025). "Moreover, we observed a similar but milder and more slowly progressive retinal degeneration in zygotic bbs1 mutants." (PMID 35277505, 2022). "A role for Bbs1/BBSome in OS maintenance is however clear, based on the subsequent appearance of morphological anomalies, first of OSs, then of photoreceptors, with slowly progressive retinal degeneration." (PMID 35277505, 2022). "Recently, it was reported that, in BBS10, the onset and progression of retinal degeneration occur earlier and faster, respectively, than in BBS type 1 (BBS1), another common subtype." (PMID 36125046, 2022). "Taken together, these results demonstrate that Bbs1 loss-of-function does not affect expression levels of other BBSome subunits or alter developmental pathways during eye formation, but rather leads to an upregulation of pro-apoptotic genes at later stages in response to retinal degeneration." (PMID 35277505, 2022). "Retinal features in both BBS1 and BBS10-RCD cohorts showed advanced retinal degeneration with optic disc pallor, blood vessel attenuation, retinal thinning, and maculopathy, as published previously and are not specific to BBS." (PMID 34940782, 2021). "In addition, they showed a progressive retinal degeneration that is characteristic of BBS and is anatomically and functionally distinguishable from the phenotypes of the BBS1 mouse model." (PMID 36125046, 2022). "Thus, for the three largest subgroups of patients BBS10 (20 patients), BBS1 (15 patients) and BBS9 (five patients) there is a similar pattern of retinal degeneration." (PMID 35886001, 2022).
retinal degeneration (continued). "The natural history of the BBS1 and BBS10-related retinal degeneration remains somewhat incomplete as in many cases the age at which the ERG became nondetectable could not be captured and was possibly earlier than documented." (PMID 34940782, 2021). "Bbs1-/- mutant mice are obese, lack sperm flagella, and develop retinal degeneration, but do not exhibit either the polydactyly or renal abnormalities observed in human BBS-affected individuals." (PMID 26540106, 2015).
Insulin resistance (7 papers, 2015 to 2025). Increased resistance towards insulin, that is, diminished effectiveness of insulin in reducing blood glucose levels. "Our results demonstrate that patients with mutations in BBS10 have significantly higher levels of C-peptide indicating insulin resistance, supporting the suggestion that they are at higher risk of cardiovascular disease than patients with mutations in BBS1." (PMID 24611735, 2015). "Moreover, POMC neuron Bbs1 gene deletion caused glucose intolerance and insulin resistance, whereas loss of the Bbs3 gene in these same neurons is associated with normal insulin sensitivity and mild glucose intolerance." (PMID 38223458, 2024). "In addition, some studies have observed lower insulin resistance measured by HOMA-IR and lower abdominal fat index for variants of the BBS1 gene compared to the BBS10 gene." (PMID 33138063, 2020).
Retinal dystrophy (5 papers, 2017 to 2024). Retinal dystrophy is an abnormality of the retina associated with a hereditary process. "However, retinal dystrophy was less severe in patients with BBS1 than in those with BBS10 variants." (PMID 28143435, 2017).
Hydrocephalus (4 papers, 2013 to 2021). Hydrocephalus is an active distension of the ventricular system of the brain resulting from inadequate passage of CSF from its point of production within the cerebral ventricles to its point of absorption into the systemic circulation. "In addition, our BBS1 conditional knockout mice are not blind nor obese and BBS8 conditional knockout mice do not have hydrocephalus, yet both models have impaired long-term context fear conditioning." (PMID 33886537, 2021).
Anosmia (3 papers, 2011 to 2022). An inability to perceive odors. "It was reported that some proteins known to cause renal cystic disease (NPHP6;BBS1, and BBS4) also localize to the olfactory epithelium (OE), and thatmutations in these proteins can cause anosmia in addition to renal cysticdisease." (PMID 21614130, 2011). "Furthermore, the mutation of proteins (NPHP6; BBS1, and BBS4) in olfactory epithelium can result in anosmia as well as renal cystic disease." (PMID 33274190, 2020).
cone-rod dystrophy (3 papers, 2021 to 2022). Inherited retinal dystrophies that belong to the group of pigmentary retinopathies. "A total of 16 patients (26%) were found to have a cone or cone-rod dystrophy, but it appears to be distributed evenly between BBS subtypes (3/15 BBS1, 2/3 BBS2, 3/3 BBS3, 1/5 BBS9, 5/20 BBS10, and 2/3 BBS12)." (PMID 35886001, 2022). "The retinal phenotype of BBS1 is typically described as RP-like rod-cone dystrophy; however, BBS10 may occur as a cone-rod dystrophy, or even an isolated cone dystrophy." (PMID 36125046, 2022).
breast carcinoma (2 papers, 2021 to 2022). "For example, it was revealed that, together with the molecular subtype, the expression signature of BBS1 was significantly related to the bone metastasis status of breast cancer and encoded mainly membrane-bound molecules with molecular function of protein binding." (PMID 35568861, 2022). "Furthermore, BBS1 was part of a 15-gene signature associated with bone metastasis in breast carcinomas." (PMID 34316711, 2021).
dyslipidemia (2 papers, 2025). "Comparisons of patients with variants in BBS1 vs BBS10 have found BBS10 pathogenic variants to result in an increased disease severity as identified through increased incidence and risk for kidney disease, metabolic syndrome, CVD, and severity of childhood obesity." (PMID 39919037, 2025).
Glucose intolerance (2 papers, 2023 to 2024). Glucose intolerance (GI) can be defined as dysglycemia that comprises both prediabetes and diabetes. "Interestingly, loss of BBS1 in POMC neurons led to glucose intolerance and insulin insensitivity, whereas BBS3 deficiency in these neurons is associated with slight impairment in glucose handling, but normal insulin sensitivity." (PMID 38223458, 2024).
Meckel syndrome (2 papers, 2023). "Comparison of the model trained on BBS1 genes to models trained on known disease gene sets shows that BBS1 model is highly similar to Meckel syndrome (both 8 and 1), which is a disease closely related to BBS1." (PMID 36721325, 2023).
morbid obesity (2 papers, 2016 to 2025). An excess of body weight, normally defined as an individual with a body mass index greater than 35 or a body weight greater than one hundred percent of ideal body weight. "Bbs1;CreLRb mice developed morbid obesity as a result of hyperphagia and reduced energy expenditure, in contrast to Ift88;CreLRb mice, which showed mild weight gain that was not a result of hyperphagia." (PMID 27482817, 2016). "Significant adiposity has been described in BBS10-related BBS; six of our ten participants with morbid obesity had BBS10-related BBS, while three had BBS1-related BBS." (PMID 40087798, 2025).
myopia (2 papers, 2023 to 2025). "For example, individuals with BBS1 mutations exhibited a mix of myopia and hyperopia, while those with BBS10 mutations were predominantly myopic with significantly higher rates of myopia compared to BBS1." (PMID 40731764, 2025).
Nystagmus (2 papers, 2017 to 2022). Rhythmic, involuntary oscillations of one or both eyes related to abnormality in fixation, conjugate gaze, or vestibular mechanisms. "We did find a significant difference between BBS gene-association with respect to the occurrence of nystagmus (p = 0.005), with 68% of BBS10 patients suffering from nystagmus and only 21% of those with BBS1." (PMID 35886001, 2022). "Genotype-phenotype correlation revealed that the six patients with biallelic mutations in BBS1 (aged 9 to 70 years) had a BCVA ranging from light perception to 0.3 decimals; four of them had a BCVA equal to or better than 1/10, three patients had nystagmus and five exotropia." (PMID 28143435, 2017). "Fourteen (70%) of the 20 BBS10 patients suffered from nystagmus, and 4/5 (80%) of the BBS9 patients but only 4/15 (27%) patients with BBS1." (PMID 35886001, 2022).
retinitis pigmentosa (2 papers, 2016 to 2019). Retinitis pigmentosa (RP) is an inherited retinal dystrophy leading to progressive loss of the photoreceptors and retinal pigment epithelium and resulting in blindness usually after several decades. "Previously, we described a family with a homozygous mutation in BBS1 leading to a mild phenotype of retinitis pigmentosa." (PMID 31541798, 2019). "Previously, we identified a family affected by retinitis pigmentosa caused by the homozygous BBS1 splice donor site mutation c.479G > A. The mutation leads to both exon 5 skipping and intron 5 retention." (PMID 31541798, 2019). "For example, apparently non-syndromic patients with retinitis pigmentosa may carry pathogenic variants in the Bardet-Biedl syndrome gene, BBS1." (PMID 27788217, 2016).
Type 2 diabetes (2 papers, 2022 to 2024). "First, in the family GBB23 with two siblings with biallelic BBS1 variants causing a clinical diagnosis of BBS, the proband also carries a third missense allele in ALMS1 (p.(His3880Tyr)), developed type 2 diabetes mellitus (T2DM)." (PMID 35835773, 2022).
allergic rhinitis (1 paper, 2014). Inflammation of the nasal mucous membranes caused by an IgE-mediated response to external allergens. "Interestingly, there was also induction of ciliary genes (BBS1, NEBL, NME7) of which NEBL and NME7 in allergic rhinitis patients with or without asthma while BBS1 exclusively in patients with allergic rhinitis." (PMID 24475887, 2014).
aortic stenosis (1 paper, 2017). Aortic valve stenosis is a aortic valve disease caused by the incomplete opening of the aortic valve. "In the two patients with potential triallelism, the clinical picture of the patient with biallelic mutations in BBS2 and one putative pathogenic missense change in BBS1 was particularly serious; in fact, this patient was born with a severe congenital aortic stenosis." (PMID 28143435, 2017).
brain inflammation (1 paper, 2012). "This decrease in inflammation following immunotherapy with mAb BBS1 compared to control mAb provides for an increased margin of safety relative to other immunotherapies for which brain inflammation has been observed in clinical trials." (PMID 23071606, 2012).
cryptorchidism (1 paper, 2020). The failure of one or both testes of a male fetus to descend from the abdomen into the scrotum during the late part of pregnancy.
cystic kidneys (1 paper, 2024). "Although pathogenic BBS1 variants are associated with cystic kidneys, they must be biallelic." (PMID 37962562, 2024).
developmental delay (1 paper, 2021). "The most prevalent extraocular features were digital anomalies (postaxial polydactyly, syndactyly, or brachydactyly), present in 96% of patients with BBS1 and 82% of patients with BBS10; followed by developmental delay, poor coordination, and kidney and liver anomalies." (PMID 34940782, 2021).
dilated cardiomyopathy (1 paper, 2019). Cardiomyopathy which is characterized by dilation and contractile dysfunction of the left and right ventricles. "Furthermore, Bbs1 gene mutation isassociated with higher susceptibility to congenital cardiac defects, heart valves andatrioventricular canal defects, dextrocardia and dilated cardiomyopathy." (PMID 31034522, 2019).
end-stage renal disease (1 paper, 2025). "In the present study, end-stage renal disease requiring dialysis was identified in one participant with BBS7-related BBS, one with BBS9-related BBS, and one with BBS1-related BBS." (PMID 40087798, 2025).
Leber congenital amaurosis (1 paper, 2022). Leber congenital amaurosis (LCA) is a retinal dystrophy defined by blindness and responses to electrophysiological stimulation (Ganzfeld electroretinogram (ERG)) below threshold, associated with severe visual impairment within the first year of life. "Although gene therapy has achieved success in treating other ocular genetic diseases such as Leber congenital amaurosis (LCA) with FDA-approved treatment, a pre-clinical gene therapy study in mouse models based on BBS1 overexpression in the wild type retina was shown to cause cytotoxicity." (PMID 36077104, 2022).
malignant pleural mesothelioma (1 paper, 2021). A malignant neoplasm that arises from mesothelial cells in the pleura and shows a diffuse growth pattern. "More interesting is the fact that higher expression of BBS1 was related to better survival in patients with malignant pleural mesothelioma, although in our PAAD signature this gene was down-regulated." (PMID 34316711, 2021).
kidney disease (5 papers, 2018 to 2025). "The present study confirms that severe kidney disease is more commonly identified in patients with pathogenic variants in BBS10 compared to BBS1." (PMID 35112343, 2022).
cardiovascular disease (2 papers, 2015 to 2022). "Generally, BBS10 and BBS2 patients have been reported as having more severe features than BBS1 with lower risk of cardiovascular disease." (PMID 35886001, 2022). "Patients with missense mutations in BBS1 have lower biochemical cardiovascular disease markers compared with patients with BBS10 and other BBS1 mutations." (PMID 24611735, 2015). "This suggests that patients with missense mutations in BBS1 may be at lower risk of cardiovascular disease than patients with BBS10 or other mutations in BBS1." (PMID 24611735, 2015).
infection (2 papers, 2013 to 2020). The state of being infected such as from the introduction of a foreign agent such as serum, vaccine, antigenic substance or organism. "Leishmania BBS1 knock-out mutants have reduced infectivity for in vivo macrophagesand infection of BALB/c mice was severely compromised." (PMID 32209228, 2020). "Loss of BBS1 does not prevent the infection of macrophages by metacyclic promastigotes or differentiation into intracellular amastigotes but BBS1 null parasites are unable to persist or induce production of a lesion in a mouse footpad model of infection." (PMID 23998526, 2013).
cancer (1 paper, 2021). A tumor composed of atypical neoplastic, often pleomorphic cells that invade other tissues. "Some of these genes (e.g. CENPF, MLKL, TFDP1, MCF2L) have a known influence on cancer, while others (e.g. NUP54, BBS1 and HTT) have been superficially studied under the tumoral context." (PMID 34316711, 2021).
BBS1 also shares sentences with these, for which no sentence is quoted: hypogonadism (3 papers); renal cystic disease (3); Alström Syndrome (2); arterial hypertension (2); cone dystrophy (2); genetic disease (2); Joubert syndrome (2); asthma (1); Bardet-Biedl syndrome 1 (1); Batten disease (1); Blindness (1); congenital generalized lipodystrophy (1); Congenital Malformations (1); cyst (1); Exotropia (1); Frasier syndrome (1); holoprosencephaly (1); Hypercholesterolemia (1); Hyperechogenic kidneys (1); hyperlipidemia (1); hyperopia (1); hypertension (1); hypothyroidism (1); Intellectual disability (1); learning disabilities (1); Leigh syndrome (1); Lipedema (1); Liver fibrosis (1); metabolic disorders (1); mucolipidosis (1).
A further 12 diseases each share a sentence with BBS1 in 1 paper.